SHD (Src homology 2 domain containing transforming protein D)
Description:
May function as an adapter protein.
Tractability: No criterion of Open Targets' tractability assessment is met for any kind of drug.
Gene: Protein-coding gene on chromosome 19 (4,279,030 to 4,290,725, forward strand). Ensembl gene ENSG00000105251.
Subcellular location (Human Protein Atlas): Centriolar satellite; Cytosol
Gene Ontology:
Molecular function: protein binding; phosphotyrosine residue binding
Genetic constraint (gnomAD): Loss-of-function variants: 34 observed, 34.89 expected, observed/expected ratio (o/e) 0.97, 90% interval 0.74 to 1.3. The upper end of that interval is the gene's LOEUF score, 1.3, which puts it in group 5 of 6, group 1 being the genes least tolerant of losing a copy. Missense variants: 520 observed, 473.02 expected, observed/expected ratio (o/e) 1.1, 90% interval 1.02 to 1.18. Synonymous variants: 208 observed, 197.58 expected, observed/expected ratio (o/e) 1.05, 90% interval 0.94 to 1.18.
Homologues: Orthologues: chimpanzee SHD (99% identical), dog SHD (89% identical), pig SHD (89% identical), guinea pig SHD (84% identical), macaque SHD (78% identical), mouse Shd (77% identical), rat Shd (74% identical), zebrafish shdb (58% identical), zebrafish shda (42% identical), tropical clawed frog shd (40% identical). Paralogues in human: SHF (50% identical), SHB (49% identical), SHE (39% identical).
Diseases named in the same sentence as SHD in open-access papers:
SHD is named in the same sentence as 7 diseases in open-access papers, as found by Europe PMC text mining. Sharing a sentence is not in itself a finding about the gene and the disease. The quoted sentences say what the papers report.
artery obstructions (1 paper, 2021). "Increased expressions of the CSRNP3, FUT10, SHD, NAV2-AS4, and hsa-mir-181 genes resulted in significance with the complexity of coronary artery obstructions or correlated with a functional cardiac benefit from bypass surgery." (PMID 34926599, 2021).
breast carcinoma (1 paper, 2019). "DMBA-induced breast cancer rats showed up-regulated levels of ICDH, SHD, MDH, and α-KGDH, and AX-SLN significantly (p < .001) down-regulated the level of mitochondrial TCA cycle enzymes such as ICDH, SHD, MDH, and α-KGDH." (PMID 31556759, 2019).
glioma (1 paper, 2022). A benign or malignant brain and spinal cord tumor that arises from glial cells (astrocytes, oligodendrocytes, ependymal cells). "In conclusion, FGFBP3, VAX2, and SHD were protective prognostic biomarkers against Macrophage M2 infiltration in low-grade glioma." (PMID 35432538, 2022).
insulin resistant (1 paper, 2018). "Here we show that MGF upregulates SHD at both expression and activity levels in quadriceps of not only wild type mice but also, importantly, in obese and insulin resistant mice." (PMID 29315239, 2018).
spinal muscular atrophy, type IV (1 paper, 2022). Proximal spinal muscular atrophy type 4 (SMA4) is the adult-onset form of proximal spinal muscular atrophy characterized by muscle weakness and hypotonia resulting from the degeneration and loss of the lower motor neurons in the spinal cord and the brain stem nuclei. "Src Homology 2 Domain Containing Transforming Protein (SHD) was over expressed in the cortex and frontal cortex, having a close relationship with spinal muscular atrophy type IV." (PMID 35432538, 2022).
tumor (1 paper, 2009). "This suggests that pro-differentiating agents, such as BMPs, may promote a metabolic shift toward oxidative phosphorylation in tumor cells and that BMP2, by decreasing intracellular succinate through induction of SHD activation, may increase PHD2 activity leading to HIF-1α modulation." (PMID 19587783, 2009).
SHD also shares sentences with these, for which no sentence is quoted: paraganglioma (1 paper).